CXCR1 (C-X-C motif chemokine receptor 1)
Description:
Receptor to interleukin-8, which is a powerful neutrophils chemotactic factor. Binding of IL-8 to the receptor causes activation of neutrophils. This response is mediated via a G-protein that activates a phosphatidylinositol-calcium second messenger system.
Synonyms: CD181; CMKAR1; IL8RA; CKR-1; CDw128a; C-C; C-C-CKR-1; CD128; IL8R1; IL8RBA
Tractability: Small molecule: a drug acting on it is in phase 2 or 3 trials; a high-quality ligand is known; it belongs to a druggable protein family. Antibody: its Gene Ontology location is reachable by antibodies, with high confidence; UniProt places it where antibodies can reach, with medium confidence; UniProt predicts a signal peptide or a membrane-spanning region. PROTAC: a small molecule that binds it is known.
Target class: Peptide receptor (family A GPCR); Membrane receptor; Family A G protein-coupled receptor; CXC chemokine receptor; Chemokine receptor
Gene: Protein-coding gene on chromosome 2 (218,162,841 to 218,166,962, reverse strand). Ensembl gene ENSG00000163464.
Subcellular location: Cell membrane
Pathways (Reactome):
Signal Transduction: Chemokine receptors bind chemokines; G alpha (i) signalling events
Immune System: Neutrophil degranulation
Gene Ontology:
Molecular function: interleukin-8 binding; interleukin-8 receptor activity; protein binding; C-C chemokine binding; C-C chemokine receptor activity; chemokine receptor activity; G protein-coupled receptor activity; C-X-C chemokine receptor activity
Biological process: cell surface receptor signaling pathway; interleukin-8-mediated signaling pathway; receptor internalization; calcium-mediated signaling; dendritic cell chemotaxis; G protein-coupled receptor signaling pathway; immune response; neutrophil activation; neutrophil chemotaxis; positive regulation of cytosolic calcium ion concentration; regulation of chemotaxis; respiratory burst; chemokine-mediated signaling pathway; chemotaxis
Cellular component: G protein-coupled receptor complex; external side of plasma membrane; plasma membrane; secretory granule membrane; membrane
Genetic constraint (gnomAD): Loss-of-function variants: 0 observed, 0.9 expected, observed/expected ratio (o/e) 0, 90% interval 0 to 1.75. That is too few expected variants to judge how well the gene tolerates losing a copy. Missense variants: 419 observed, 454.87 expected, observed/expected ratio (o/e) 0.92, 90% interval 0.85 to 1. Synonymous variants: 180 observed, 190.98 expected, observed/expected ratio (o/e) 0.94, 90% interval 0.83 to 1.07.
Homologues: Orthologues: chimpanzee CXCR1 (96% identical), macaque CXCR1 (92% identical), rabbit CXCR1 (84% identical), guinea pig Cxcr1 (72% identical), mouse Cxcr1 (64% identical), rat Cxcr1 (60% identical), tropical clawed frog cxcr2 (55% identical), zebrafish cxcr2 (42% identical). Paralogues in human: CXCR2 (77% identical), CCR6 (38% identical), CXCR3 (37% identical), CCR4 (34% identical), CCR9 (33% identical), CXCR4 (33% identical), CXCR5 (33% identical), CCR7 (33% identical), ACKR2 (31% identical), CCR2 (30% identical), CCR1 (30% identical), CCR8 (29% identical), and 11 more.
Diseases named in the same sentence as CXCR1 in open-access papers:
CXCR1 is named in the same sentence as 257 diseases in open-access papers, as found by Europe PMC text mining. Sharing a sentence is not in itself a finding about the gene and the disease. The quoted sentences say what the papers report.
breast carcinoma (104 papers, 2010 to 2025). "The CXCR1 gene polymorphism has been predominantly linked to a range of human diseases, including ovarian cancer, hepatocellular carcinoma, and breast cancer, and is implicated in tumor proliferation, metastasis, and angiogenesis." (PMID 40428307, 2025). "Gallegos-Arreola demonstrated that the CXCR1 gene polymorphisms rs1008562, rs2234671, and rs3138060 are associated with an increased susceptibility to human breast cancer." (PMID 40428307, 2025). "CXCR1/2 ligands are associated with Ras/MAPK transcriptional activity in breast cancer cell lines and tumors." (PMID 32634121, 2020). "Reparixin is an investigational small-molecule allosteric inhibitor of CXCR1, which has been shown to reduce BCSCs in human breast cancer xenografts in mice, both alone and in concert with chemotherapy." (PMID 40869256, 2025). "Small molecule inhibitors of CXCR1/2 have been explored: reparixin was tested in early breast cancer trials to target breast cancer stem cells by blocking CXCR1, which also binds IL-8." (PMID 41007766, 2025). "For instance, targeting Lgr5 in colorectal cancer, DLL3 in pulmonary neuroendocrine tumors, and CXCR1 in breast cancer has been reported to reduce the CSC population." (PMID 39420119, 2024). "In two clinical trials to eliminate the activity of breast cancer stem cells (BCSCs) with bevacizumab (VEGF inhibitor) (NCT01190345) or reparixin (CXCR1/2 inhibitor) (NCT01861054), ALDH1A1 is one of the markers to measure the effect of drugs on BCSC activity." (PMID 36694633, 2023). "The administration of repertaxin, a small-molecule CXCR1 inhibitor, alleviated tumor development and decreased the progression of breast cancer metastasis in NOD/SCID mice." (PMID 37762330, 2023). "Breast cancer cells are reported to secrete IL-8, express CXCR1/2, and promote breast cancer initiation and progression, as well as tumor cell migration and invasion." (PMID 36835413, 2023). "Interleukin (IL)-8 plays a vital role in regulating inflammation and breast cancer formation by activating CXCR1/2." (PMID 37762330, 2023). "Through patient sample analysis, the Yao research group found a correlation between breast cancer relapse, metastases, and CXCR1 expression." (PMID 36831112, 2023). "A window-of-opportunity study on breast cancer also showed that Reparixin, an oral tablet of CXCR1/2 inhibitor, reduced the cancer stem cells (CSCs) content and appeared safe and well-tolerated among the treated patients." (PMID 36624516, 2023). "For the future of CXCR1-targeted therapy in breast cancer therapy, we need to see how it affects patient outcomes." (PMID 36831112, 2023). "CXCR1 has been reported to be important for the renewal of a population of stem cell-like cells in human breast cancer." (PMID 37270599, 2023). "Of note, a higher expression of the mRNA levels of CXCR1/2 was found in basal breast cancer subtype in relation to the luminal A, luminal B, ERBB2 and normal-like molecular subgroups." (PMID 35954247, 2022). "Targeting CXCR1/2 by a small inhibitor repertaxin reversed tamoxifen resistance of BQ overexpressing breast cancer cells in vitro and in vivo." (PMID 35054486, 2022). "Breast cancer MICs express CXCR1 and CXCR2, and both receptors help to establish and maintain a stemness phenotype and induce EMT, thus contributing to metastasis." (PMID 36118530, 2022). "Repaxirin is an investigational inhibitor of CXCR1 that has been shown to reduce the CSC content of human breast cancer in mice xenografts, which is already in phase II clinical trials (NCT02370238, NCT01861054)." (PMID 35326385, 2022). "In lung and breast cancer, the combined inhibition of CXCR1/2 by using the SX-682 inhibitor and anti-PD-1/PD-L1 has effectively controlled tumor growth in a murine model." (PMID 36091114, 2022). "CXCR1 was also found to be expressed by various cancers, including breast cancer stem cells and malignant melanoma, and blocking it using an anti-CXCR1 (repertaxin) resulted in reduced survival." (PMID 35453930, 2022).
breast carcinoma (continued). "Nicely fitting with these data, the blockade of IL-8 by a neutralizing antibody or the inhibition of CXCR1/2, blunted tumor growth and metastasis, and also reversed the resistance to treatments in breast cancer." (PMID 35954247, 2022). "Our findings assessed for the first time the role of the AGEs/RAGE signaling pathway in breast CAFs and its involvement in the paracrine stimulation of the IL-8/CXCR1/2 axis toward the acquisition of malignant features of breast cancer cells." (PMID 35954247, 2022). "Consistent with our findings, IL-8 and CXCR1/2 inhibitors significantly attenuated progression of breast cancer." (PMID 35130902, 2022). "A prior study examining breast cancer stem cells demonstrated that these cells express high levels of the IL-8 receptor CXCR1 and that IL-8 promotes cancer stem cell self-renewal." (PMID 33822772, 2021). "SX-682 is in clinical trials for melanoma (NCT03161431) and other CXCR1/2 inhibitors are in trials for combination therapies in breast cancer." (PMID 34725321, 2021). "Repartaxin is a small molecule inhibitor of CXCR1 and has been demonstrated to have therapeutic efficacy in preclinical models of breast cancer and gastric cancer." (PMID 34540690, 2021). "Like CXCR2, CXCR1 is expressed significantly in breast cancer stem cells, which increases the growth of breast cancer when stimulated by inflammation or tissue damage." (PMID 33747948, 2021). "The utilization of reparixin, a small molecular weight antagonist of CXCR1/2 as a breast cancer therapeutic agent has been investigated in preclinical and clinical studies." (PMID 33747948, 2021). "To date, key roles were identified in breast cancer for CXCR1/CXCR2 and their CXCL1/CXCL8 ligands in promoting resistance to chemotherapeutic drugs such as doxorubicin and paclitaxel." (PMID 32582148, 2020). "This is consistent with other studies, showing that the IL-8/CXCR1 pathway is essential for CSCs survival in breast cancer." (PMID 33059744, 2020). "For example, a CXCR1 blockade has been shown to selectively target breast cancer stem cells and its expression has been correlated with poor prognosis in breast cancer." (PMID 30873179, 2019). "The inhibitor of CXCR1/2, reparixin, has been effective in human breast cancer xenografts, and a phase Ib clinical trial has been completed in patients with metastatic breast cancer." (PMID 31013960, 2019). "CXCR1 was identified as a druggable target on breast cancer CSC identified by the expression of ALDH, while its expression was almost undetectable on bulk (i.e., non-CSC) tumor cells." (PMID 30788286, 2019). "Reparixin is an allosteric inhibitor of IL-8 (CXCL8) receptor CXCR1/2 and has the activity against BCSCs in xenografts of breast cancer." (PMID 30175384, 2018). "Reparixin is an allosteric inhibitor of IL-8 (CXCL8) receptor CXCR1/2 has the activity against BCSCs in xenografts of breast cancer." (PMID 30175384, 2018). "Ligation of the IL-8 receptor CXCR1 by IL-8 in breast cancer cells increases cancer stem cell self-renewal thereby expanding the pool of cancer stem cells." (PMID 28860143, 2018). "Recent reports in the cancer literature indicate that IL-8, signaling through CXCR1/2, promotes cancer stem cell self-renewal, stimulating mammosphere colony formation in breast cancer stem cells." (PMID 28860143, 2018). "Chemokine receptor CXCR1 was lowly expressed in normal breast tissues and breast fibroadenoma, but highly expressed in breast cancer." (PMID 28454081, 2017). "At the same time, articles also have been reported that CXCR1 plays an important role in the development and treatment of breast cancer." (PMID 28454081, 2017). "Breast cancer cells do express CXCR1 and CXCR2, and increasing evidence indicates that IL-8 plays a critical role in enhancing the invasive and metastatic potential of breast cancer cells." (PMID 29021819, 2017). "This study found that after neo-adjuvant chemotherapy, the expression of CXCR1 in breast carcinoma decreased." (PMID 28454081, 2017).
breast carcinoma (continued). "Chemokine receptor CXCR1 was expressed in different degrees in normal breast tissues, breast fibroadenoma and breast cancer tissues." (PMID 28454081, 2017). "A mouse model for human breast cancer in this study revealed that during the therapy of breast cancer, adding drugs to block CXCR1 would help kill breast cancer stem cells to improve treatment effect." (PMID 28454081, 2017). "Recently the chemokine receptor CXCR1 has also been reported to have an important role in the progression of breast cancer." (PMID 28454081, 2017). "The PI of CXCR1 in normal breast tissue, breast fibroadenoma and breast carcinoma were 1.6 ± 0.57, 2.3 ± 0.48 and 5.9 ± 0.95 respectively; which gradually increased." (PMID 28454081, 2017). "The relationship between the CXCR1 expression changes in breast cancer biopsies and surgical specimens, as well as the efficacy of neo-adjuvant chemotherapy, was analyzed." (PMID 28454081, 2017). "We analyzed the PIs of expression of CXCR1 in each biopsy and surgical specimen and found that its expression in breast cancer was higher than that in normal breast tissue and breast fibroadenoma." (PMID 28454081, 2017). "It is necessary to study and explore the role of CXCR1 in the development of breast cancer and the feasibility of this targeted therapy." (PMID 28454081, 2017). "This study detected the expression of CXCR1 in normal breast tissue, breast fibroadenoma and breast carcinoma by using immunohistochemical method." (PMID 28454081, 2017). "In other words, the expression of chemokine receptor CXCR1 had been greatly decreasing in the process of neo-adjuvant chemotherapy for breast cancer, and there was a positive correlation between the expression of CXCR1 and neo-adjuvant chemotherapy response." (PMID 28454081, 2017). "Accordingly, IHC staining showed that only tumor cells within orthotopic 1° IRISOE-driven mammary tumors express CXCR1." (PMID 29262555, 2017). "It was previously shown that IL-8 and its receptor CXCR1 are protagonists especially in breast cancer stem cells." (PMID 26840266, 2016). "The IL-8/CXCR1/CXCR2 signaling axis is critical for the establishment of stem-like properties in breast cancer." (PMID 27531902, 2016). "Recently, the IL-8/CXCR1 axis was proposed as an attractive pathway for the design of specific therapies against breast cancer stem cells." (PMID 26517518, 2015). "The IL-8/CXCR1 axis was recently proposed as an attractive pathway for the design of specific therapies against breast cancer stem cells." (PMID 26517518, 2015). "Our findings indicate that MUC1-C contributes to the self-renewal of breast cancer cells by activating the NF-κB→IL-8/CXCR1 pathway and that targeting MUC1-C represents a potential approach for the treatment of this population." (PMID 24770886, 2014). "It has been reported that breast cancer stem cells express CXCR1, which upon binding of CXCL8 increase their activity (measured as sphere-formation) and self-renewal." (PMID 25165728, 2014). "Our results identify IL8 and its receptor CXCR1 as potential targets for the treatment of breast cancers with active HER2/HER3/IL8 signaling." (PMID 23062209, 2012). "IL-8 expression was increased in mammospheres and treatment of IL-8 increased the mammosphere number of breast cancer cells and blockage of CXCR1 signaling by repertaxin reduced chemoresistance of BCSCs." (PMID 22023707, 2011). "Concerning IL-8 receptors, it has been observed that CXCR1 expression was extremely low in breast cancer cells, whereas most of the cells investigated showed a higher expression of CXCR2." (PMID 20540789, 2010). "Therefore, we verified the effect of IL-8 on the growth of breast cancer cells using breast cancer cell lines with CXCR1 knockdown and CXCR2 knockdown." (PMID 40839237, 2025). "Breast cancer is the first tumor where CXCR1 was recognized as a CSC marker." (PMID 36831112, 2023).
breast carcinoma (continued). "This suggests that strategies focused on intervening in the IL-8/CXCR1 axis may be capable of targeting CSCs and decreasing the growth of breast cancer, increasing the usefulness of present therapies." (PMID 37762330, 2023). "AGE-RAGE signalling prompted interaction between breast cancer cells and cancer-associated fibroblasts (CAFs), via up-regulation of IL-8 (pro-inflammatory cytokine) levels in CAF with ensuing paracrine stimulation of CXCR1/2 (chemokine receptors)." (PMID 37970208, 2023). "Moreover, the IL-8/CXCR1/2 system correlates with poor clinical prognosis in diverse types of tumor, including breast cancer." (PMID 35954247, 2022). "Reparixin, a clinical grade CXCR1/2 inhibitor, suppresses breast cancer growth in vitro." (PMID 33603130, 2022). "Likewise, the evaluation of the Kaplan–Meier survival curves revealed a worse clinical outcome in basal breast cancer patients showing high CXCR1/2 levels." (PMID 35954247, 2022). "Pre-clinical studies demonstrate that combining CXCR1/2 inhibitors with the human epidermal growth factor receptor 2 (HER2)-targeted therapies has potential as an effective treatment strategy to repress CSCs activity in breast cancer." (PMID 35372515, 2022). "Hence, CXCR1/2 can be a possible target for developing a therapeutic agent against tamoxifen resistance in breast cancer." (PMID 35054486, 2022). "Interestingly, in a gene expression profile study, CXCR1 was found to be upregulated in ALDH+ BCSCs of various breast cancer cell lines." (PMID 35326385, 2022). "In addition, the survival analysis performed on the basal breast cancer subtype revealed that a worse relapse free survival (RFS) characterizes patients exhibiting a high expression of CXCR1/2." (PMID 35954247, 2022). "In fact, this same group developed a functionalized PAMAM, with a multi-targeted nanosystem using anti-HER2 VHH (deriving from single chain variable library) coupled to CXCR1 promoter, PE38 toxin A gene and bFGF 5′UTR which selectively caused cytotoxicity in HER2-positive Breast Cancer Stem Cells." (PMID 36136517, 2022). "Next, we aimed to evaluate whether IL-8 secreted by CAFs may promote a feed-forward loop that engages CXCR1/2 toward the acquisition of certain malignant features in the MDA-MB-231 breast cancer cells, which express elevated CXCR1/2 levels." (PMID 35954247, 2022). "Indeed, IL-8 can stimulate osteoclastogenesis, the hallmark of breast cancer bone metastasis, indirectly via increasing the RANKL on osteoblasts or directly via CXCR1 on osteoclasts." (PMID 33809315, 2021). "IL-8 regulates breast cancer stem cell activity by binding to C-X-C motif chemokine receptor 1/2." (PMID 32977636, 2020). "Blocking the CXCR1/IL8 axis has been suggested to selectively target CSCs in breast cancer." (PMID 31709178, 2019). "In view of the role of IL-8 in mediating BCSC self-renewal and breast cancer chemoresistance, several IL-8 releasing inhibitors, small-molecule CXCR1/2 inhibitors and neutralizing antibodies against IL-8 and CXCR1/2 have been reported during the past two decades." (PMID 30175384, 2018). "Breast cancer patients treated with chemotherapeutic drugs exhibited poor survival rate and shorter disease-free survival time if their tumor samples expressed high level of IL-8, or its receptor, CXCR1, CXCR2." (PMID 30175384, 2018). "CXCR1 is thought to be a receptor selectively expressed in breast cancer stem cells (BCSCs)." (PMID 30175384, 2018). "Furthermore, oncology research has suggested that blocking CXCR1 can inhibit the differentiation of breast cancer stem cells, and that CXCR1 is overexpressed in the development of malignant melanoma and involved in cell growth and angiogenesis." (PMID 30123110, 2018). "CXCR1 is thought to be a receptor selectively expressed in breast cancer stem cells." (PMID 30175384, 2018).